GNAI2P1 (G protein subunit alpha i2 pseudogene 1)
Synonyms: formerly GNAI2A; GNAI2L
Gene: Transcribed processed pseudogene on chromosome 12 (14,254,912 to 14,255,226, forward strand). Ensembl gene ENSG00000255749.
Diseases named in the same sentence as GNAI2P1 in open-access papers:
GNAI2P1 is named in the same sentence as 1 disease in open-access papers, as found by Europe PMC text mining. Sharing a sentence is not in itself a finding about the gene and the disease. The quoted sentences say what the papers report.
tumor (1 paper, 2023). "Based on recent research, GNAI2P1 mutations impaired its tumor suppressive function and promoted tumor progression." (PMID 37945594, 2023).